NTN1 (netrin 1)
Diseases named in the same sentence as NTN1 in open-access papers (continued):
Sharing a sentence is not in itself a finding about the gene and the disease.
metabolic disorders (3 papers, 2022 to 2025). "Future research should explore the functional consequences of modulating this axis and assess the clinical relevance of Netrin-1 as a biomarker or therapeutic target in metabolic disease." (PMID 40949120, 2025).
bone disorder (1 paper, 2024). "Thus, the specific modulation of DCC and UNC5B via netrin-1 may serve as a promising strategy to treat bone disorders." (PMID 38628640, 2024). "Regarding their roles in bone disorders, UNC5B, as a downstream effector of netrin-1, has been shown to prevent bone destruction, and DCC has been reported to be expressed in a CD166-positive subpopulation of chondrocytes in human osteoarthritic cartilage." (PMID 38628640, 2024). "Even though netrin-1 along with its downstream effectors is well known to be involved in the modulation of bone metabolism and contributes to the progression of various bone disorders, their roles in the development of DOP are not well understood." (PMID 38628640, 2024). "Therefore, it is reasonable to assess whether the specific modulation of netrin-1 and its downstream effectors can serve as a promising strategy for treating DOP and other bone disorders." (PMID 38628640, 2024).
brain diseases (1 paper, 2024). "These insights shed light on the mechanisms underlying Netrin-1-mediated microglia colonization and underscore its therapeutic significance in microglia-related brain diseases." (PMID 39000184, 2024). "Together, our findings highlight the role of Netrin-1 in microglia migration and underscore its therapeutic potential in microglia-related brain diseases." (PMID 39000184, 2024).
colon polyps (1 paper, 2014). "This view was supported by studies using transgenic overexpression of netrin-1 in the apical surface, which suppressed cell death and induced colon polyps in mice." (PMID 24720832, 2014). "Netrin-1 expression was shown to be expressed in the base of the crypts and forced expression in apical surface suppresses cell death, which leads to the formation of colon polyps." (PMID 24720832, 2014).
NTN1 also shares sentences with these, for which no sentence is quoted: schizophrenia (7 papers); prostate tumors (3); acute myeloid leukemia (2); adenocarcinoma (2); benign tumors (2); cleft palate (2); liver (2); oligodendroglioma (2); preeclampsia (2); renal dysfunction (2); skin squamous cell carcinoma (2); acute myocardial infarction (1); age (1); amyotrophic lateral sclerosis (1); anaplastic oligoastrocytoma (1); angina (1); arteriosclerosis obliterans (1); astrocytic tumor (1); autism spectrum disorder (1); autoimmune disease (1); basal cell carcinoma (1); benign prostate hyperplasia (1); breast ductal carcinoma (1); carbon monoxide poisoning (1); cerebral (1); chronic allograft nephropathy (1); cognitive disorder (1); coinfection (1); congenital hypothyroidism (1); coronary artery disease (1).
A further 53 diseases each share a sentence with NTN1 in 1 paper.